RNF212B (ring finger protein 212B)
Description:
Ubiquitin E3 ligase that acts as a crucial factor for crossing-over (CO) formation during meiosis. Essential for normal prophase I progression and for ensuring appropriate CO designation in meiosis. Recruits key components of the cross-over machinery either directly ou indirectly, leading to the activation of the MutL-gamma complex. The function of RNF212B in CO designation is dependent on its catalytic activity.
Synonyms: C14orf164
Tractability: PROTAC: UniProt records ubiquitination sites on it.
Gene: Protein-coding gene on chromosome 14 (23,185,316 to 23,273,477, forward strand). Ensembl gene ENSG00000215277.
Subcellular location: Chromosome
Subcellular location (Human Protein Atlas): Golgi apparatus; Nucleoli; Nucleoli fibrillar center; Nucleoplasm
Gene Ontology:
Molecular function: SUMO transferase activity; ubiquitin protein ligase activity
Biological process: chiasma assembly; homologous chromosome pairing at meiosis; protein ubiquitination; reciprocal meiotic recombination
Cellular component: chromosome; synaptonemal complex
Genetic constraint (gnomAD): Loss-of-function variants: 10 observed, 16.96 expected, observed/expected ratio (o/e) 0.59, 90% interval 0.36 to 1. The upper end of that interval is the gene's LOEUF score, 1, which puts it in group 4 of 6, group 1 being the genes least tolerant of losing a copy. Missense variants: 77 observed, 106.01 expected, observed/expected ratio (o/e) 0.73, 90% interval 0.6 to 0.88. Synonymous variants: 25 observed, 33.73 expected, observed/expected ratio (o/e) 0.74, 90% interval 0.54 to 1.03.
Homologues: Orthologues: chimpanzee RNF212B (99% identical), macaque RNF212B (87% identical), dog RNF212B (85% identical), rabbit RNF212B (83% identical), mouse Rnf212b (79% identical), rat Rnf212b (77% identical), tropical clawed frog rnf212b (39% identical), zebrafish rnf212b (30% identical), Caenorhabditis elegans zhp-3 (21% identical), Caenorhabditis elegans zhp-4 (19% identical), Caenorhabditis elegans zhp-2 (18% identical), Caenorhabditis elegans zhp-1 (15% identical), and 2 more. Paralogues in human: RNF212 (16% identical).
Diseases named in the same sentence as RNF212B in open-access papers:
RNF212B is named in the same sentence as 2 diseases in open-access papers, as found by Europe PMC text mining. Sharing a sentence is not in itself a finding about the gene and the disease. The quoted sentences say what the papers report.
Infertility (2 papers, 2023 to 2025). "Factors that ensure crossing over between each pair of homologs include mammalian RING-domain proteins RNF212, HEI10, and RNF212B, alleles of which are linked to infertility and heritable variation in crossover rate." (PMID 39761402, 2025).
male infertility (1 paper, 2023). The inability of the male to effect fertilization of an ovum after a specified period of unprotected intercourse. "Here, we report the discovery of a rare, recessive, nonsense mutation in a previously uncharacterized gene called Ring Finger Protein 212B (RNF212B), as the probable causative variant of male infertility in two brothers with OAT and repeated unexplained MAR failures." (PMID 37124137, 2023). "We further associated the loss of RNF212B function with impaired spermatogenesis and a high rate of aneuploidy in the affected sperm and the derived embryos, accounting for this severe familial case of male infertility." (PMID 37124137, 2023).